LEP (leptin)
Diseases named in the same sentence as LEP in open-access papers (continued):
Sharing a sentence is not in itself a finding about the gene and the disease.
Obesity (continued). "Such a fat-induced blockade of leptin transport across the BBB seems maladaptive from an obesity-point of view (which in fact would be worsened by this mechanism)." (PMID 26041981, 2015). "Intravenously injected Ad-leptin effectively facilitated repair of the ischemic femoral head and enhanced angiogenesis and bone regeneration in rats with induced obesity." (PMID 25797953, 2015). "This suggests that prolonged elevation of GH disrupts normal physiological responses to elevated plasma leptin, creating leptin resistance and obesity; in the case of elevated GH, the most likely site of leptin signaling impairment is at the hypothalamic axis." (PMID 25774292, 2015). "LEP resistance appears to be a mechanism that is a part of the burden of obesity on health that extends across multiple organ systems." (PMID 26783391, 2015). "For decades, mammalian leptin has been under intense study as potentially playing a role in obesity." (PMID 25919309, 2015). "One key hormone in breast milk is leptin, related with the protection from obesity in the adulthood, thus knowing its changes through the day or lactation is crucial." (PMID 26680765, 2015). "Recently, obesity and its related proteins like leptin were studied in the diabetic population of Pakistan." (PMID 26273663, 2015). "In summary, in the presence of genetic or obesity-induced concurrent insulin and leptin resistance, Kiss1 neurons are able to maintain reproductive function." (PMID 25946091, 2015). "High levels of circulating leptin in adipose tissues characterise human obesity and increased levels of body fat." (PMID 25873982, 2015). "This implies that the higher leptin levels seen in obese individuals should result in lower SWT and LVMI, but obesity is associated with LVH." (PMID 26064110, 2015). "Obesity is accompanied by increased release of free fatty acids (FFAs) and altered secretion of adipokines such as leptin, adiponectin, resistin and retinol-binding protein-4 (RBP-4) from adipocytes." (PMID 26110385, 2015). "The elevation in sympathetic nerve activity induced by leptin is believed to contribute to obesity induced hypertension." (PMID 26617526, 2015). "Rat portal veins were treated with leptin at a concentration of 3.1 nmol/L (50 ng/mL) due to its equivalence to leptin concentrations in obesity for 24 h and the ratio of F/G-actin was calculated and normalized to unstretched (untreated) RPVs." (PMID 26557089, 2015). "Combined, these results show that impaired signaling through GluN2B-NMDARs in AgRP neurons of diabetic and obese mice causes a major improvement in blood glucose control and increases sensitivity to leptin's anti-obesity actions." (PMID 26500840, 2015). "At molecular level, the major transcription factors such as PPAR γ, C/EBP α, C/EBP β, SREBP-1c and expression of FAS, FABPs, leptin, adiponectin, and AMPK-1α have been implicated in regulating obesity." (PMID 25887331, 2015). "Leptin is present in serum concentrations directly proportionate to adipose tissue mass and is shown to be elevated in human obesity." (PMID 26064978, 2015). "The effect of leptin, which is generally attenuated in obesity, is preserved in the renal sympathetic nervous system." (PMID 26495973, 2015). "In lean subjects, leptin circulates principally in the bound form while in obesity the leptin circulates mainly as a free form due to small sOB-R concentrations." (PMID 26180527, 2015). "Thereby, these studies support that several mediators of inflammation are related with hyperleptinemia and leptin resistance development in states of obesity induced by diet." (PMID 26474157, 2015). "The original findings used renal sympathetic nerve activity as the neural output to show that the sensitivity to leptin was retained in obesity." (PMID 26617526, 2015).
Obesity (continued). "Out of all pure adipokines, plasma levels of which were measured in the study; exclusively leptin, a marker of obesity, exhibited higher-than-normal values in both obese groups, while visfatin and resistin remained within the normal range (data not shown)." (PMID 26090072, 2015). "In the current study, PCOS and the obesity status increases leptin level and decresaes the soluble leptin receptor." (PMID 26180527, 2015). "The present study examines the relationship between obesity, leptin and AMI in Chennai based population." (PMID 25762868, 2015). "Most studies examining the roles of CORT, insulin and leptin in obesity and behavior have used adrenalectomized rats, which require complicated surgery." (PMID 25754523, 2015). "The discovery that the leptin gene LEP is "the obesity gene" (OB; i.e., LEP ≡ OB) shed light on the regulation of energy metabolism." (PMID 26694100, 2015). "Leptin was identified as the first adipokine in 1994 and is able to promote the progression of diabetes, obesity, and atherosclerosis." (PMID 26457306, 2015). "In this condition, obesity impairs pulmonary ventilation and affects various respiratory components, e.g., leptin resistance." (PMID 26274965, 2015). "Despite the relative disappointment of leptin as a blockbuster drug for obesity, the study of leptin’s biology has literally revolutionized the way we understand the physiology of appetite and metabolic regulation." (PMID 25177314, 2014). "Calorie restriction (CR), an effective anti-obesity strategy with potent anticancer effects, has been shown to reduce serum levels of insulin, leptin, and IGF-1 and decrease the expression of protumorigenic cytokines." (PMID 24804677, 2014). "The expression and secretion of leptin, resistin, and TNF-α have been associated with the progression of obesity, while the adiponectin has been shown to be inversely related with obesity and has anti-inflammatory and anti-atherosclerotic properties." (PMID 24932656, 2014). "Our study is in agreement with previous evidence that circulating blood concentrations of adiponectin and leptin vary by race and obesity." (PMID 25197277, 2014). "Leptin has been proposed to be responsible for some of the beneficial effects of breastfeeding and is thought to be involved in preventing infants to obesity." (PMID 25415449, 2014). "In summary, peripheral hormonal signals released from the GI tract (ghrelin, PYY, GLP-1, and CCK), pancreas (insulin), and adipose tissue (leptin) constitute a key component in the gut-brain axis-mediated control of appetite, energy expenditure, and obesity." (PMID 25412152, 2014). "In this regard, leptin and other fat derived inflammatory mediators have been proposed as a link between obesity and allergy." (PMID 24405509, 2014). "At 16 weeks of age, CPEfat/fat mice develop severe obesity, hyperglycemia, elevated serum triglycerides and leptin, and increased blood neutrophil counts." (PMID 25203099, 2014). "The discovery of leptin in 1994 raised the possibility of new therapeutic strategies to combat obesity epidemic." (PMID 25352831, 2014). "This is because leptin biosynthesis increases under conditions of obesity, due in part to enhanced post- and pre-transcriptional effects of insulin and glucocorticoids." (PMID 25375630, 2014). "The correlation of TSH with leptin was an accidental finding at the end of the day, which needs to be investigated for further research on leptin and its effects on obesity and metabolic impairments." (PMID 25587271, 2014). "The presence of obesity, insulin resistance, hyperandrogenemia, and infertility in PCOS resemble those found in “ob/ob” leptin deficient rats." (PMID 25587271, 2014). "Numerous recent studies have shown that secretion of proinflammatory cytokines (interleukin 6, TNF Alpha, MCP – 1, leptin) is increased in obesity; whereas, the concentration of anti-inflammatory cytokines (adiponectin, interleukin 10) is decreased." (PMID 24387137, 2014).
Obesity (continued). "In agreement with reduced diet-induced obesity, serum leptin levels were also lower after a high fat diet in both global and fat-specific Alk7 knock-out mice." (PMID 25161195, 2014). "The present revision emphasizes the mechanism of OA genesis directly related to the level of circulating leptin in obesity." (PMID 25184806, 2014). "Adiponectin and leptin exhibited opposing and variable correlations with obesity, IR and the components of the metabolic syndrome." (PMID 25276234, 2014). "Sympathomimetic state induced by poor sleep quality reduces leptin level and elevates ghrelin level, which is also related with obesity." (PMID 24903537, 2014). "Leptin most likely indicates satiety and fullness of energy stores under physiological conditions, but obesity is characterized by hyperleptinemia and hypothalamic leptin resistance." (PMID 25215659, 2014). "To evaluate the anti-obesity effect of fGT, we assessed body weight, fecal excretion, serum leptin levels, exocrine pancreatic zymogen granule contents, and periovarian fat weight and adiponectin contents." (PMID 25207824, 2014). "Diet-induced obesity has been shown to impair AMPK regulation by leptin, insulin, and sympathetic neural efferent’s in other tissues, and aspects of AMPK function appear to be restored with weight loss." (PMID 24849657, 2014). "Because of its crucial role in controlling satiety and body weight, leptin triggered a frenetic enthusiasm, after its discovery in 1994, with the perspective of using leptin therapy to treat obesity." (PMID 25352831, 2014). "As obesity evolves, leptin transport becomes saturated, and immunologic processes are blocked: Th1 cell differentiation no longer occurs, and cytokine production is diminished." (PMID 25076128, 2014). "The most common and striking feature of all six leptin-related rodent models is their early and severe obesity." (PMID 24809394, 2014). "One of these hormones is leptin, which was identified in 1994 and has attracted the attention of obesity researchers." (PMID 24981337, 2014). "Various studies have demonstrated that increased leptin levels and obesity are inversely related to cognitive decline in menopausal women." (PMID 25251414, 2014). "Leptin is regarded as a proinflammatory cytokine: its production is increased as the degree of obesity increases and adiponectin, an anti-inflammatory cytokine, is inhibited when levels of proinflammatory cytokines increase." (PMID 25324698, 2014). "Leptin levels in obese human subjects are the best hormonal predictor of obesity-related reduction in androgen response to hCG tests in vivo." (PMID 24829619, 2014). "Recently, treatment with a CB1 inverse agonist was shown to reverse leptin resistance and reduce obesity in diet induced obese mice." (PMID 25610411, 2014). "Leptin is the biochemical and immunologic link that connects obesity to decreased vaccine immune response; it is an adipocyte-derived cytokine and a hormone." (PMID 25076128, 2014). "Three genes, MC4R, LEP and POMC, have been identified through genetic association to confer an increase in obesity susceptibility and are also environmentally responsive to dietary intake." (PMID 25127133, 2014). "Further, leptin insensitivity exacerbates HPA dysregulation in obesity and thereby enhances the mass of dysfunctional central adipose stores in a cortisol-dependent manner." (PMID 25225489, 2014). "Leptin, an adipocyte-derived hormone is involved in appetite regulation, insulin homeostasis and obesity through the effects of the hypothalamus." (PMID 24944619, 2014). "The therapeutic potential of these compounds has now to be determined in the context of leptin resistance and obesity treatment." (PMID 25352831, 2014). "Recently, a momentous advancement is that two groups simultaneously unmasked the involvement of MFNs in diet-induced obesity via the regulation of leptin resistance and systemic energy metabolism." (PMID 24658162, 2014).
Obesity (continued). "Referring to current clinical recommendations, a sequencing of the leptin gene in patients with extreme early-onset obesity is suggested only in the presence of undetectable or very low serum leptin levels." (PMID 26567097, 2014). "Aim of study was to investigate the relationship between leptin levels and age, gender, anthropometric parameters, lipid parameters, arterial hypertension (AH), and obesity in the adult population of ethnic Kyrgyz people living in Central Asia." (PMID 24981337, 2014). "In fact, elevated leptin levels in obesity inhibit insulin signaling and enhance the IR effect, which leads to an increase in intracellular fatty acids and deposition of triglycerides (TG) in the hepatocytes." (PMID 24838072, 2014). "This study aimed to analyse the impact of obesity in type 2 diabetes (T2D) on adipocytokines (adiponectin, leptin and resistin) and inflammatory markers (TNF-α, IL-6 and hsCRP) as cardiovascular risk factors." (PMID 24736687, 2014). "Leptin-deficient POMC gene mutation, MCR4 gene mutation need also to be considered among the monogenic causes of early-onset obesity." (PMID 25541898, 2014). "Disruption of the gene encoding IKK and the innate immune system receptor Toll-like receptor (TLR)-4 in mice confers protection from insulin and leptin resistance, and obesity in mouse models." (PMID 24675731, 2014). "The mechanisms of obesity began to be eluciated after the anti-obesity hormone leptin was identified." (PMID 24421337, 2014). "The current review will focus on the different emerging therapeutic strategies in obesity research that are related to leptin and its receptor." (PMID 25352831, 2014). "In total, 50 obese patients undergoing bariatric surgery were included, and paired samples of visceral adipose tissue (VAT) and subcutaneous adipose tissue (SAT) were examined for gene expression of obesity markers leptin, adiponectin and TNFα and PPARγ." (PMID 24427296, 2014). "In basic research, ob/ob mice, db/db mice, Zucker fatty rats and ZDF rats have been extensively used to study the pathogenesis of T2DM, obesity, leptin signaling, and the interactions among the three." (PMID 24809394, 2014). "The most important adipocytokines modified during development of obesity are leptin and adiponectin." (PMID 25324698, 2014). "First, the degree of obesity in our Japanese patients was much less than that of the studies performed in European countries, which demonstrated a resistance to leptin-induced vasoreactivity in human subjects with obesity or MetS." (PMID 24410779, 2014). "Adipose-derived hormones changed in MSG obesity rats: adiponectin decreased by 58.8% (p < 0.01), and leptin concentration in adipose tissue had increased by 74.7% (p < 0.01)." (PMID 24410812, 2014). "Leptin seems to be directly related to obesity by maintaining energy homeostasis with decreased food intake and increased energy expenditure." (PMID 25587271, 2014). "In contrast, transgenic mice with OBRb Y985S mutation, which lost SOCS3 binding site, showed decreased food intake, increased leptin sensitivity and are protected from high-fat diet-induced obesity." (PMID 25352831, 2014). "Adipocytokines such as leptin and adiponectin play important roles in the metabolic regulation of obesity and obesity-related complications." (PMID 25375161, 2014). "The different BMI quartiles were then compared in order to further evaluate the association between obesity and levels of CRP and leptin." (PMID 24944619, 2014). "Three main adipokines, resistin, adiponectin and leptin are adipocyte-secreted molecules that act as core contributors to the development or regulation of obesity, insulin resistance and hepatic steatosis." (PMID 24879081, 2014). "The db/db mouse is a well-established animal model for analyzing diabetic dyslipidemia and MetS, which precipitates obesity, insulin resistance, hyperglycemia, and leptin resistance." (PMID 24666525, 2014).
Obesity (continued). "Since leptin secretion from adipose tissues is positively correlated with TG accumulation in adipocytes, plasma leptin level is a biomarker in assessing obesity in both experimental animals and humans." (PMID 24817902, 2014). "Despite the dismal clinical data for leptin in the treatment of obesity, recent work has renewed interest in leptin’s clinical translation." (PMID 26237477, 2014). "While leptin functions to reduce appetite and increase energy expenditure, resistance to leptin’s effects is well documented in metabolic complications, such as obesity." (PMID 25610411, 2014). "Caffeic acid also exhibited antiobesity effects by reducing body and visceral fat-pad weights, plasma levels of lipids, and obesity-related hormones such as leptin and insulin in HFD-fed mice." (PMID 24624222, 2014). "Hypothalamic inflammation is considered a key pathology of obesity in rodents and humans, leading to central leptin resistance through activation of the negative regulators of leptin signaling, SOCS and PTP1B." (PMID 24675731, 2014). "Since obesity is characterized by leptin resistance, further studies should examine if the effects of leptin, as found in the present study, can be confirmed in PDL cells from obese individuals." (PMID 25136363, 2014). "Previous research has established that changes in the expression of SOCS3, leptin, and the activation of STAT3, and AMPK are linked to the regulation of insulin signaling in obesity and diabetes." (PMID 24997069, 2014). "Obese individuals exhibit higher circulating levels of leptin, contributing to a state of leptin resistance, which further perpetuates obesity, inflammation, and metabolic disease." (PMID 24967364, 2014). "Current clinical recommendations suggest sequencing of the leptin gene in cases of extreme early childhood obesity preferably in the presence of undetectable to low serum leptin levels." (PMID 26567097, 2014). "Leptin, ghrelin, and insulin-like growth factor-1 are also known to be important mediators in acceleration of T-cell immunosenescence by obesity." (PMID 24651652, 2014). "ADCY3 knockout mice exhibit age-dependent obesity, which was attributed to hyperphagia, low locomotor activity, and leptin insensitivity and demonstrated to be most likely because of hypothalamic cAMP reductions." (PMID 25044758, 2014). "Global deletion of PrRP (in a loxSTOPlox-PrRP mouse) results in obesity and attenuated responses to leptin and CCK." (PMID 25176149, 2014). "The responsiveness of C57BL/6 ksr2−/− mice to leptin distinguishes them from murine models of obesity including the ob/ob mouse, db/db mouse, SHROB rat, JCR:LA‐cp rat, Zucker rat, and ZDF rat model systems." (PMID 24997067, 2014). "In particular, the genes responsible for the monogenic form of obesity are leptin, leptin receptor, melanocortin receptor 4, proopiomelanocortin, prohormone convertase 1, and Agouti related protein." (PMID 25110685, 2014). "After its discovery in 1994, leptin became the great hope as an anti-obesity treatment based on its ability to reduce food intake and increase energy expenditure." (PMID 25352831, 2014). "To further examine epigenetic regulation of the leptin expression, we detected CpG methylation at the leptin promoter and the mRNA expression during development of obesity." (PMID 24923522, 2014). "Leptin concentration in the blood is elevated in obesity, promoting a leptin resistance that renders the elevated leptin futile in curbing appetite and obesity." (PMID 25412152, 2014). "Certainly there is enough evidence to link leptin plasma levels as a function of cellular resistance and obesity, especially in menopausal women." (PMID 25251414, 2014). "Nonetheless, in pathological conditions such as obesity or metabolic syndrome (MetS), resistance to leptin’s vasodilatory effect has been observed in both animal and human studies." (PMID 24410779, 2014).